INS (insulin)
Diseases named in the same sentence as INS in open-access papers (continued):
Sharing a sentence is not in itself a finding about the gene and the disease.
cancer (continued). "Besides its role as a transcription factor in stressed cells, HSF1 is involved in a multitude of physiological processes such as cell metabolism, gametogenesis, aging, insulin signaling, and cancer progression." (PMID 27446966, 2016). "IGF-1 and insulin share overlapping downstream signaling pathways in normal and cancer cells." (PMID 27405474, 2016). "This could have potentially provided escape mechanisms for insulin and IGF-2 signaling that have been implicated in cancer cell progression, leading to limited clinical response." (PMID 27127884, 2016). "Conversely, insulin significantly enhanced cancer cell migration and invasion." (PMID 26939025, 2016). "The high circulatory levels of glucose and/or insulin or the application of exogenous insulin may promote carcinogenesis, cancer progression and metastasis, which can be attributed to the Warburg effect or aerobic glycolysis." (PMID 26939025, 2016). "Fourth, individuals receiving insulin usually visit their doctors more frequently, and this may increase their probability of screening and cancer detection." (PMID 25916213, 2016). "Another gene, RFWD2 (COP1) is a cancer suppressor and effects human β-Cell Insulin Secretion." (PMID 28117656, 2016). "Currently it is recommended that the general population participate in moderate intensity exercise on most days of the week to improve insulin sensitivity, but the optimal volume and intensity of exercise needed to improve insulin sensitivity in cancer survivors still needs to be determined." (PMID 27781180, 2016). "Elevated blood glucose may promote cancer progression and lead to poor outcomes via pathways mediated high levels of insulin and insulin-like growth factor." (PMID 28003023, 2016). "Increased blood insulin and glucose are conducive to cancer cell growth." (PMID 26959117, 2016). "Most cancer cells express insulin and insulin-like growth factor (IGF), which could stimulate insulin-mediated mitogenesis and cancer cell proliferation and metastasis." (PMID 26927312, 2016). "Several reports showed the involvement of stimulation of IR by insulin or IGF-2 in cancer cell progression suggesting that IGF-1R and IR both are therapeutic targets and inhibition of both receptors may be required for optimal tumor growth inhibition." (PMID 27127884, 2016). "IGF-1 and insulin share overlapping downstream pathways of cancer cell metabolism." (PMID 27405474, 2016). "Moreover, FoxO1 shows the most abundance in insulin-responsive tissues (e.g., liver) and its dysregulation has been found in several human cancers." (PMID 26893361, 2016). "While evidence of higher angiolymphatic invasion could be consistent with previous reports implying exogenous insulin as a growth factor for cancer cells, lower Ki67 is inconsistent with this postulation." (PMID 27648070, 2016). "It is hypothesized that metformin’s anti-cancer effects are mediated by systemic effects via decreasing both insulin and glucose and by direct effects on cancer cells through activation of critical signaling pathways, including AMP-activated kinase (AMPK)." (PMID 26788855, 2016). "The aim of this study was to determine whether combining insulin with metformin reduced the risk of all-cause mortality, major adverse cardiac event (MACE), or cancer compared with insulin monotherapy, taking insulin dose into account." (PMID 27152598, 2016). "Insulin use is significantly predictive for mortality from both cancer and non-cancer death." (PMID 27906989, 2016). "Insulin has been confirmed to be capable of stimulating glucose uptake in many cancer cells, which may promote the Warburg effect." (PMID 26939025, 2016). "Patients treated with insulin plus concomitant metformin did not have a statistically significantly reduced risk of cancer (0.96, 0.80–1.15) when compared with those treated with insulin monotherapy." (PMID 27152598, 2016). "Insulin use is significantly predictive for a higher risk of mortality from either cancer or non-cancer death." (PMID 27906989, 2016).
cancer (continued). "We also analysed cancer mortality by censoring the first 12 months of insulin use (Model 10)." (PMID 27031113, 2016). "Additionally, the few RCTs on insulin therapy that have reported data on cancer have focused on mortality." (PMID 25916213, 2016). "Data regarding the influence of insulin analogues on cancer incidence are inconsistent." (PMID 27648070, 2016). "Our findings have potentially strong implications to understanding normal developmental processes that involve Notch4 function as well as cancer pathogenesis by providing a novel link between insulin and growth factor-activated AKT signaling and the transcriptional regulator Notch4." (PMID 25740432, 2015). "Metformin attenuates cancer growth indirectly through reduction in serum insulin and IGF–1 concentration caused by improvement in insulin sensitivity, and directly through cell cycle arrest and inhibition of mammalian target of rapamycin (mTOR) following AMPK activation." (PMID 26439622, 2015). "Overall, the pre-clinical evidence strongly supports the hypothesis that insulin/IGF signaling promotes the progression of numerous cancer types." (PMID 26029167, 2015). "Therefore, further research should be warranted to assess the clinical feasibility of insulin in cancer patients." (PMID 26271039, 2015). "Isothiocyanates, such as sulforaphane (SFN), allyl-isothiocyanate (AITC), phenethyl-isothiocyanate (PEITC), and benzyl-isothiocyanate (BITC) possess numerous health-related effects, and these compounds have been shown to inhibit cancer and inflammation and improve insulin sensitivity." (PMID 26317351, 2015). "With regard to cancer mortality, we did not detect significant association with insulin use (12 studies; RR = 1.19, 95% CI 0.80–1.77)." (PMID 26076034, 2015). "Using many types of cancer cells and genetically engineered mice, it has been demonstrated that IGFs and insulin promote cancer cell proliferation, motility, invasion, and survival, and augmentation of these activities is proposed as a mechanism for cancer development, growth, and metastasis." (PMID 26074875, 2015). "Finally, several trials have combined insulin/IGF-targeting drugs with EGFR inhibitors in a number of different cancers based on pre-clinical studies showing that EGFR signaling mediates resistance to IGF-IR inhibition and vice versa." (PMID 26029167, 2015). "The association of insulin response pathway with splicing regulation in cancer has not been reported before, and its functional implication will be an interesting subject of future studies." (PMID 25749525, 2015). "However, there is controversy regarding the pro-mitogenic effects as the mechanisms of insulin/IGF-1 in promotion of cancer development." (PMID 26268733, 2015). "As many tumours devise means to evade regulations of growth factor signaling, we propose that insulin may serve as the spark to initiate cancer development at early stages when self-sufficiency of growth factors has not yet been established." (PMID 25961014, 2015). "In addition to its anti-cancer effect, in recent studies with cachectic mice bearing colon-26 tumors, rosiglitazone treatment improved insulin sensitivity and attenuated skeletal muscle protein degradation during early cachexia." (PMID 25807446, 2015). "Half receptors of insulin exist as two splice variant isoforms, “A” and “B.” While the “B” isoform recognizes only insulin, the “A” isoform recognizes both insulin and IGF-2 and is expressed most commonly by cancer cells." (PMID 25866823, 2015). "Routine physical activity may produce alterations in immune function, oxidative damage, and the insulin axis that may impact cancer metabolism." (PMID 26147495, 2015). "Researchers have also examined whether insulin/IGF signaling impacts cancer prognosis and have generally found that circulating insulin levels appear to be more predictive than the IGFs." (PMID 26029167, 2015). "Accumulated evidence suggests that excess IGF/insulin activity contributes to cancer development." (PMID 26074875, 2015).
cancer (continued). "Hence, therapy of NAFLD with insulin-sensitizing drugs should ideally improve the key hepatic histological changes, while also reducing cardiometabolic and cancer risks." (PMID 25875942, 2015). "The link between insulin and P-glycoprotein in contribution to cancer chemoresistance may also correlate with β-catenin." (PMID 26084465, 2015). "Since insulin is produced by pancreatic β-cells and then transported via the portal vein to the liver, long-term exposure of growth factor (insulin) may case the higher incidences of cancer in pancreas and liver." (PMID 25978841, 2015). "These cancer-specific AS events are highly conserved, are more likely to maintain protein reading frame, and mainly function in cell cycle, cell adhesion/migration, and insulin signaling pathways." (PMID 25749525, 2015). "Moreover, IGFR-1, also proposed to be involved in cancer, can hybridize with the IR to bind insulin and stimulate cell proliferation." (PMID 25849721, 2015). "Thus, collectively, insulin/IGF signaling in cancer and its therapeutic targeting still warrants further investigation." (PMID 25699021, 2015). "The insulin/IGF system plays an important role in cancer progression." (PMID 25798130, 2015). "Importantly, we have discovered that a large number of DEGs in “pathways in cancer”, “insulin signaling”, and “MAPK signaling pathway” are upregulated by Ras1CA overexpression in the PSG." (PMID 24606580, 2014). "and insulin-producing cells, the dose of CoQ0 that gives selective toxicity to cancer cells should be examined in more detail before it can be considered for use in cancer chemotherapy." (PMID 25431605, 2014). "Our results showed a weaker association for IGF-1 driven cancers than the overall association or non-hormonally driven cancers, suggesting that if the insulin- IGF- 1 axis does play a role it is likely to be as part of a more complex molecular mechanism." (PMID 25526881, 2014). "Importantly, Ras1CA overexpression in the PSG upregulated many DEGs distributed in “pathways in cancer”, “insulin signaling pathway”, and “MAPK signaling pathway” as well as “purine metabolism” and “pyrimidine metabolism”." (PMID 24606580, 2014). "Consistently, treatment with insulin, metformin, sulphonylurea and TZD was associated with 40% to 80% reduced cancer risk after adjusting for co-variables, drug indications, use of other drugs, and lipid-associated risk factors for cancer." (PMID 24886453, 2014). "Further studies are required to unravel whether the IR-A is involved in the development of cancers and whether, in this respect (some) insulin analogs differ from human insulin." (PMID 24904529, 2014). "In a previous analysis using validated methods (that is, a sensitivity analysis with use of the time-fixed Cox model), insulin users had a 51% risk reduction in cancer risk compared with non-users, probably due to insulin’s effects on blood glucose lowering." (PMID 24886453, 2014). "The start of insulin treatment within 0–3 years after the initiation of OADM was associated with a higher cancer risk, RR being 3.12 [95% CI 1.12–6.72] when no adjustment was performed." (PMID 25419576, 2014). "SH2-containing inositol 5′-phosphatase 2 (SHIP2) belongs to the phosphoinositol phosphatases family which plays important role in modulating signaling pathways relevant to both diabetes and cancer and generally regulates insulin signaling, cytoskeleton remodeling, and receptor endocytosis." (PMID 25525286, 2014). "Notably, these 22 pathways included the insulin signaling, as well as a number of other functional processes involved in development, cell growth, cancer, and immunity." (PMID 24400080, 2014). "Some results showed that insulin use would increase cancer risk, while others suggested that insulin did not play a role in cancer development." (PMID 24885616, 2014).
cancer (continued). "Furthermore, the knockdown of PKM2 expression also inhibited cancer cell growth and insulin-induced glucose consumption and lactate production, suggesting that PKM2 is a functional downstream effecter of insulin." (PMID 24895527, 2014). "While OGLD results are to be “interpreted” mostly as adjustments, it is of great interest to note that no insulin type was associated with any possible harm as regards cancer mortality." (PMID 24667573, 2014). "Additionally, we found that the levels of IRS-2, a central modulator of insulin signalling in normal and cancer cells and a target of microRNA33a as well were modulated by metformin." (PMID 24980829, 2014). "First, excess secretion of insulin and insulin-like growth factor, a cancer cell promoter, may be inhibited as a result of improved insulin sensitivity resulting from physical activity." (PMID 25261876, 2014). "Insulin has been shown to affect VGSC expression/activity also in non-cancer cells." (PMID 24493753, 2014). "Insulin is a growth promoting hormone and acts by increasing cell proliferation, decreasing apoptosis, increasing glucose utilization, and enhancing responsiveness to other growth factors; all of these actions are important for cancer progression." (PMID 25426078, 2014). "The role of insulin during cancer progression has been debated." (PMID 25373319, 2014). "It is fairly accepted that in the post-developmental stage of life, GH and IGF1 have numerous beneficial actions in skeletal muscle and cardiovascular and nervous systems, but a negative effect on insulin sensitivity and cancer risk." (PMID 24683479, 2014). "Nowadays, much has been known on the role of insulin use in cancer, several systematic reviews and meta-analysis, both on observational and interventional studies, have reported the harmful effect of insulin on cancer." (PMID 24885616, 2014). "The autocrine and paracrine secretion of insulin and insulin-like growth-factors (IGFs) 1 and 2 are key regulators of metabolism and growth, which subserve energy production and growth stimulation, respectively, in cancer cells." (PMID 24885964, 2014). "Moreover, reduction of circulating insulin levels using a beta 3-adrenergic receptor agonist (CL-316243) or downregulation of the IR in cancer cells and xenografts decreased tumor growth and reduced cell proliferation and metastasis." (PMID 25114970, 2014). "Metformin may act at the organismal level, reducing levels of circulating insulin, a known mitogen for cancer cells." (PMID 24843020, 2014). "Cumulative exposure time to glargine insulin was associated with a trend towards lower cancer mortality (SHR 0.96, 95% CI 0.92–1.01, p = 0.091), without reaching statistical significance." (PMID 24667573, 2014). "First, insulin is known to prompt cancer cells to divide, so the slower rate of tumor growth could just be a side-effect of the metformin reducing the amount of insulin in the blood." (PMID 24843020, 2014). "In addition, we have shown that knockdown of PKM2 expression decreased insulin-induced aerobic glycolysis and cancer cell proliferation." (PMID 24895527, 2014). "Some studies, but not all, have reported that individuals using long-acting insulin analogs have increased risk of cancer." (PMID 25373319, 2014). "As many malignant cancer cell lines encompass over-expressed 3-phosphoinositide-dependent kinase 1 or a loss of PTEN function, the anabolism activator, insulin or its mimetics, usually exacerbate AKT-mediated PGC-1α suppression and reduce mitochondrial metabolism and antioxidant defenses." (PMID 28250388, 2014). "However, the molecular mechanisms of insulin in regulating glucose metabolism of cancer remain to be elucidated." (PMID 24895527, 2014). "In another study, insulin prevented apoptosis in epithelial and cancer cells." (PMID 24745031, 2014).
cancer (continued). "On the other hand, increases in effective circulating insulin levels in an insulin-resistant state may have undesirable effects on lipids and proinflammatory cytokines, and theoretically may promote cancer progression." (PMID 26237474, 2014). "Studies performed in different cancer models revealed that insulin treatment, c-Src kinase activation and integrin-mediated mechanotransduction cause tyrosine phosphorylation of CAV1 on tyrosine 14 (Y14), which appears to be essential for CAV1-driven cell migration." (PMID 25148256, 2014). "Relative overexpression of IR-A may play a key role in the development and progression of human cancers after starting treatment with insulin (analogs)." (PMID 24904529, 2014). "Physiologically, to attenuate MetS in non-cancer persons, implementing a strictly aerobic exercise program has been found effective since aerobic exercise can reduce blood pressure, decrease triglycerides, improve insulin sensitivity, and body fat." (PMID 24708832, 2014). "All together, these data suggest that the downregulation of HSD11B2 expression in cancer colonic cell lines, after long-term insulin treatment would be the consequence of LIP overexpression, together with increased lactate production, both working at an epigenetic level." (PMID 25133511, 2014). "However, the role of ROS production in cancer cells in response to insulin-induced glucose metabolism remains to be elucidated." (PMID 24895527, 2014). "Moreover, cancer related pathways as well as insulin signaling pathways were up-regulated after rCNT exposure." (PMID 25318534, 2014). "The results did not indicate any association between the use of insulin and cancer when insulin treatment commenced more than three years after the initiation of OADM." (PMID 25419576, 2014). "In addition to its effects on metabolic functions such as glucose transport, insulin can also stimulate the growth and proliferation of cancer cells, a potential concern when either insulin or insulin analogs are employed for therapeutic purposes." (PMID 24533136, 2014). "Indeed, the strategies that target the cancer metabolism are being actively tested recently, among which targeting insulin system such as insulin inhibition and metformin has shown promising anti-tumor effect." (PMID 24970814, 2014). "Therefore, the Insulin/IGF-I signaling pathway has been considered an appealing therapeutic target in cancer." (PMID 24282611, 2013). "The role played by the introduction of insulin analogues, the choice of insulin regimens, the ongoing debate on insulin and cancer, the cardiovascular effects of insulin, the role of insulin on β-cell protection and the actual clinical perspective in the treatment of the disease." (PMID 24348585, 2013). "None of the types of insulin and oral agents analyzed showed a significant increase in the risk of cancer." (PMID 24278227, 2013). "In this study, the role of insulin in promotion of cancer metabolism is examined." (PMID 23837608, 2013). "Elevated insulin serum levels favour faster growth and increased aggressiveness of colorectal, pancreatic, liver, postmenopausal breast, and endometrial cancers." (PMID 24073332, 2013). "The role of insulin, however, in regulation of cancer cell metabolism is still obscure." (PMID 23837608, 2013). "The observations of Kalaany and Sabatini that cancer cells with constitutively activated PI3K mutations are proliferative in vitro in the absence of insulin or IGF-1 and form CR-resistant tumors in vivo illustrate this issue." (PMID 24280167, 2013). "Some results showed that insulin was associated with an increased cancer risk, while others suggested that insulin did not play a role in cancer development." (PMID 23308218, 2013). "The failure may be attributed in part to the selection of appropriate target population, and in part to the increased dependency of cancer cells on insulin." (PMID 23663564, 2013).